H2BC26 (H2B clustered histone 26)
Description:
Core component of nucleosome. Nucleosomes wrap and compact DNA into chromatin, limiting DNA accessibility to the cellular machineries which require DNA as a template. Histones thereby play a central role in transcription regulation, DNA repair, DNA replication and chromosomal stability. DNA accessibility is regulated via a complex set of post-translational modifications of histones, also called histone code, and nucleosome remodeling.
Synonyms: H2BU1; HIST3H2BB; H2Bb
Tractability: Small molecule: a structure with a bound ligand is known. PROTAC: UniProt records ubiquitination sites on it; ubiquitination databases record sites on it.
Gene: Protein-coding gene on chromosome 1 (228,458,103 to 228,463,104, forward strand). Ensembl gene ENSG00000196890.
Subcellular location: Nucleus; Chromosome
Subcellular location (Human Protein Atlas): Nucleoplasm; Cytosol
Pathways (Reactome):
Gene expression (Transcription): B-WICH complex positively regulates rRNA expression; DNA methylation; ERCC6 (CSB) and EHMT2 (G9a) positively regulate rRNA expression; MLL4 and MLL3 complexes regulate expression of PPARG target genes in adipogenesis and hepatic steatosis; NoRC negatively regulates rRNA expression; PRC2 methylates histones and DNA; RNA Polymerase I Promoter Escape; RNA Polymerase I Promoter Opening; RUNX1 regulates genes involved in megakaryocyte differentiation and platelet function; RUNX1 regulates transcription of genes involved in differentiation of HSCs; Regulation of endogenous retroelements by KRAB-ZFP proteins; Regulation of endogenous retroelements by Piwi-interacting RNAs (piRNAs); Regulation of endogenous retroelements by the Human Silencing Hub (HUSH) complex; SIRT1 negatively regulates rRNA expression; Transcriptional regulation by small RNAs
Chromatin organization: CHD1 and CHD2 subfamily; CHD6, CHD7, CHD8, CHD9 subfamily; ChAHP complex assembly; HATs acetylate histones; HDACs deacetylate histones; Interaction of NuRD complexes with transcription factors; NuRD complex assembly
DNA Repair: Cleavage of the damaged purine; Cleavage of the damaged pyrimidine; Nonhomologous End-Joining (NHEJ); Processing of DNA double-strand break ends; Recognition and association of DNA glycosylase with site containing an affected purine; Recognition and association of DNA glycosylase with site containing an affected pyrimidine; Recruitment and ATM-mediated phosphorylation of repair and signaling proteins at DNA double strand breaks
Cell Cycle: Condensation of Prophase Chromosomes; Deposition of new CENPA-containing nucleosomes at the centromere; G2/M DNA damage checkpoint; Inhibition of DNA recombination at telomere; Packaging Of Telomere Ends
Developmental Biology: Activation of anterior HOX genes in hindbrain development during early embryogenesis; Chromatin modifications during the maternal to zygotic transition (MZT); Replacement of protamines by nucleosomes in the male pronucleus; Transcriptional regulation of granulopoiesis
Disease: Defective pyroptosis; Dengue Virus-Host Interactions
and 17 more pathways
Gene Ontology:
Molecular function: DNA binding; structural constituent of chromatin; protein heterodimerization activity
Biological process: antibacterial humoral response; antimicrobial humoral immune response mediated by antimicrobial peptide; chromatin organization; innate immune response in mucosa
Cellular component: nucleus; nucleoplasm; nucleosome; chromosome
Genetic constraint (gnomAD): Loss-of-function variants: 9 observed, 6.6 expected, observed/expected ratio (o/e) 1.36, 90% interval 0.8 to 1.91. That is too few expected variants to judge how well the gene tolerates losing a copy. Missense variants: 178 observed, 178.71 expected, observed/expected ratio (o/e) 1, 90% interval 0.88 to 1.13. Synonymous variants: 113 observed, 77.56 expected, observed/expected ratio (o/e) 1.46, 90% interval 1.25 to 1.7.
Homologues: Orthologues: chimpanzee H2BC26 (100% identical), macaque H2BC26 (100% identical), mouse H2bc26 (100% identical), rat H2bu1 (100% identical), pig H2BC26 (99% identical), dog H2BC27 (97% identical), rabbit H2BC26 (52% identical). Paralogues in human: H2BC17 (97% identical), H2BC15 (96% identical), H2BC21 (96% identical), H2BC3 (96% identical), H2BC9 (96% identical), H2BC10 (95% identical), H2BC11 (95% identical), H2BC13 (95% identical), H2BC18 (95% identical), H2BC4 (95% identical), H2BC5 (95% identical), H2BC6 (95% identical), and 9 more.
Diseases named in the same sentence as H2BC26 in open-access papers:
H2BC26 is named in the same sentence as 5 diseases in open-access papers, as found by Europe PMC text mining. Sharing a sentence is not in itself a finding about the gene and the disease.
H2BC26 shares sentences with these, for which no sentence is quoted: cancer (2 papers); systemic lupus erythematosus (2); bladder carcinomas (1); breast carcinoma (1); cervical cancer (1).